TNF (tumor necrosis factor)
Diseases named in the same sentence as TNF in open-access papers (continued):
Sharing a sentence is not in itself a finding about the gene and the disease.
infection (continued). "In ileum inflammatory genes were overexpressed (e.g., IL-1B, IL-6, IL-8, IL1RAP, TNFα), indicating a strong immune response at all times of infection." (PMID 26738723, 2016). "The gene expression of the two pro-inflammatory cytokines IL6 and TNFα was also highly significantly induced 30 h post infection in the E. coli treated and in the co-stimulated samples." (PMID 27310007, 2016). "This infection-dependent increase was essentially abolished in all cases by probiotic therapy (experimental group 2) (p = 0.006 for TNF-α; p = 0.0003 for IL-6; p = 0.047 for IL-10)." (PMID 27780258, 2016). "It is acknowledged that IFN-γ is of major importance for control of T. cruzi infection and its induction is tightly regulated, whereas TNF, expressed throughout the course of infection, is of secondary importance to parasite control." (PMID 27128676, 2016). "The therapeutic 100 TCID50 group showed transient increase in the expression levels of TNF-α and IL-1β throughout the course of infection and of the IL-12p70 on days 3 and 4 after infection." (PMID 27110056, 2016). "Polarised 16HBE cells released TNF-α into the basolateral compartment after infection with B. thailandensis or F. tularensis LVS in a MOI-dependent manner." (PMID 27527221, 2016). "Our results strongly suggest that TNF-α/IL-10 plasma cytokine level, given its established role, is a mechanistically feasible biomarker that warrants further studies in burn trauma and infections." (PMID 27761434, 2016). "Overall, these results emphasize the absolute requirement of an IL8/TNF-dependent neutrophil mobilization for granuloma formation and control of Mabs infections." (PMID 27806130, 2016). "Because TNF is a major driver of inflammation in response to infection, as well as in the context of inflammatory diseases, the role of IAPs in shaping TNF-dependent inflammatory signalling is an important unresolved question." (PMID 26989333, 2016). "Specifically, IL-1RA, IFNα2 and TNFα were all elevated within the first five days of infection relative to mock-infected controls, but there was little difference in expression between Asibi virus- and mock-infected MDM." (PMID 27191161, 2016). "NQO1 expression was increased after mycobacterial infection, and NQO1 knockdown increased macrophage differentiation, NF-κB activation, and the secretion of pro-inflammatory cytokines TNF-α and IL-1β in response to infection." (PMID 27297123, 2016). "Infection of Nod2−/− macrophages induced a small increase in IL-1β production, but suppressed TNF-α production." (PMID 27670879, 2016). "Tumor necrosis factor alpha (TNFα) is one of the main pro-inflammatory cytokines produced in response to a broad type of infections." (PMID 27351838, 2016). "TNF-α is a multifunctional cytokine playing a pivotal role in the regulation of inflammation and infection via the stimulation and engagement of the specific cell surface receptor 1 (TNFR1, ZDB-GENE-040426-2252)." (PMID 27806130, 2016). "Especially, at the late infection phases (after 12 h post infection), Bp showed faster intracellular growth, stronger cytotoxicity, and higher TNF-α release." (PMID 27894256, 2016). "After infection for 24 h, different concentrations of recombinant TNF-α or IL-6 were added to the PCV2-infected PK-15 cells, which were further cultivated for 12 h." (PMID 27581515, 2016). "H56 in combination with CAF01, IC31® and GLA-SE all primed IFN-γ, IL-6 and TNF-α responses prior to infection and all of these cytokine responses remained two weeks after challenge." (PMID 26791076, 2016). "The infection induced increased expression of TNF-α, IL-1β and IL-10 in both WT and SG−/− mice, but the cytokine levels were significantly lower in the SG−/− mice." (PMID 27267469, 2016).
infection (continued). "In an endemic area of ACL caused by L. (V.)braziliensis in Brazil, it wasfound that INF-g and TNF-a levels from lymphocyte supernatants in subjects withasymptomatic infection were significantly lower than they were in patients with active ACL." (PMID 27759762, 2016). "Here, we have used the zebrafish as an infection model to examine in vitro and in vivo the mechanisms by which TNFα enhances viral pathogenesis." (PMID 27351838, 2016). "At 36 h post-infection, the qPCRs showed that TNF-α induced IL-6 expression, and higher IL-6 and TNF-α levels were induced by PCV2 when SOCS3 was silenced, compared with control cells." (PMID 27581515, 2016). "We previously identified an involvement of the CD95/CD95L and TNF-α-pathway in the phagocytosis-induced cell death of monocytes, following infection with E. coli." (PMID 27870876, 2016). "A persistent elevation of TNF-α and HMGB-1 can induce a further infiltration of neutrophils and macrophages to the site of infection, which cause an uncontrolled HIR." (PMID 27556404, 2016). "DKO-derived TEPMs produced significantly higher amounts of TNF-α than other TEPMs after infection with E. coli." (PMID 27734904, 2016). "Lastly, the number of extrapulmonary sites of infection before TNF neutralization was significantly higher in animals that would later develop reactivation compared to those that would not." (PMID 27379816, 2016). "In this research, though the magnitude and duration of each cytokine differed between the two Listeria, the trends along with infection are same, which are increase of TNF-α, IL-6, IL-12, and IFN-γ and decrease of IL-4." (PMID 27375558, 2016). "At 4 h of infection, the response was significantly different; EAEC caused a TNF-α secretion of 0.33 ng/ml while ETEC infection caused a secretion of 0.2 ng/ml of TNF-α." (PMID 27774437, 2016). "Peripheral TNF-α motivated via infection and tissue damage can cross the BBB through fast transmission pathway involving primary afferent nerves, a saturable transport system, or a slow transmission pathway." (PMID 27187381, 2016). "In human MDM, IFNα2 and TNFα were both elevated 2–5 dpi in 17D-infected cells, but the response diminished as the infection proceeded." (PMID 27191161, 2016). "IL-6 and TNFα are critical for rapid response to tissue injury and infections and induce the production of acute phase reactants in the liver whereas IL-12 is the main inducer of IFNγ in NK cells and T cells." (PMID 27548618, 2016). "At 48 and 72 h post infection, mRNA expression of IL-1β, IL-6, IL-8, and TNF-α in mimic-transfected cells was substantially decreased compared to the control mimic." (PMID 27117627, 2016). "We also describe the dramatic consequences of impaired TNF/IL8 immunity on the outcome of the infection." (PMID 27806130, 2016). "Inhibition of STAT3 signaling during infection led to an increase of the inflammatory cytokine secretion, IL-6 (26 fold) and TNF-α (5 fold), compared to control infected macrophages." (PMID 27384401, 2016). "TNF KO mice were down to 40% free alveolar space at 4 weekspost-infection, when they had to be terminated." (PMID 26931771, 2016). "Tumor necrosis factor-alpha (TNF-α) plays a crucial role in the defensive immune response to C. burnetii invasion and is responsible for early infection control." (PMID 27656302, 2016). "Infection leads to the upregulation of inflammatory cytokines, such as interleukin-1β (IL-1β), interleukin-10 (IL-10), and tumor necrosis factor-α (TNF-α)." (PMID 28105799, 2016). "Lung IL-6 and TNFα responses were similar in all the mouse strains compared to to those of wildtype mice following Ft LVS infection or SchuS4 infection." (PMID 27926940, 2016). "During the progression of inflammation, proinflammatory cytokines such as TNF-α and IL-6 are released by macrophages to protect the body from tissue injury or infection." (PMID 27890971, 2016).
infection (continued). "At the early stages of infection, TNF-α, IL-1β, IL-6, and IL-8 pro-inflammatory cytokines are produced and stimulate immune cells leading to activation of an inflammatory cascade." (PMID 28066425, 2016). "Important immune cells required for bacterial clearance are macrophages and neutrophils, which are attracted and activated to sites of infection by IL-8, IL-6, and TNF-α." (PMID 27527221, 2016). "IL-2/IFN-γ/TNF-α co-expression remained quite stable during the entire course of infection (from day 14 to day 56)." (PMID 27760221, 2016). "TNF blockade has been evaluated in clinical trials, but severe adverse events were reported including infection and malignancy." (PMID 26922672, 2016). "Infection led to a further increase in the levels of plasma pro-inflammatory cytokines including IL-6, TNF-α, KC and MIP-2." (PMID 26859674, 2016). "For example, TNF-α is elevated during infection and inflammation and has been suggested to mediate the increase in vascular leakage after acute respiratory distress syndrome and sepsis." (PMID 27603666, 2016). "TNF diffusion constant and TNF half-life are positively correlated with ECB, at later stages of the infection, which is plausible given TNF's roles in inducing apoptosis of infected macrophages." (PMID 26913242, 2016). "The production of CCL-2 did not occur until 12 h post-infection, but then increased from 24 to 48 h post-infection, while the secretion of IP-10 and TNF-α increased gradually peaking at 36 h post-infection." (PMID 28127293, 2016). "West and colleagues suggested that murine pulmonary infection induced by inhalation of B. pseudomallei leads to increases in IFN-γ, IL-10, IL-1β, IL-6, KC and TNF-α in the lung 1 day after infection." (PMID 27529172, 2016). "In the zebrafish model, a cellular adaptor protein termed factor associated with neutral sphingomyelinase activity (FAN) has been shown to co-ordinate TNF-α activated chemotaxis in response to infection and wounds." (PMID 27231948, 2016). "Using a unique in vitro model, we showed that hrHPV infection renders KCs resistant to IFNγ/TNFα-induced necroptosis and arrest of cell growth." (PMID 27920775, 2016). "Infection with the H9N2 virus leads to an increase in the expression of the pro-inflammatory cytokines TNF-α." (PMID 27826541, 2016). "The immune response triggered by the infection in injured larvae was also assayed by measuring the expression of the proinflammatory genes IL-1β and TNFα." (PMID 27540375, 2016). "During systemic bacterial infections, activated NK cells can limit tissue infection and prevent systemic spread of the pathogen through direct lysis of target cells or by releasing GM-CSF, TNF and IFNγ to orchestrate further responses." (PMID 27341123, 2016). "Increased TNF-α from the Riboflavin plus CIP or Riboflavin plus AZM treated macrophages at early infection (at 30 min) indicating bacterial killing and better efficacy of both this antibiotics in presence Riboflavin." (PMID 27932936, 2016). "Another study utilizing a HCMV clinical isolate demonstrated that early in infection, HCMV down-regulates the TNF-α receptor, perhaps as a means to modulate TNF-α responses in order to tip the host-microbe balance in favor of infection." (PMID 27182601, 2016). "In this study, TNF-α/IL-10 ratio was found to be highly predictive of hypersusceptibility to infections, with high AUROC and high sensitivity and specificity." (PMID 27761434, 2016). "Lung cells from TNF-, TNFR1-, orM-TNFR1-deficient mice and wild-type controls were analysed by flow cytometry 28days after infection, at a time when they display inflamed lung." (PMID 26931771, 2016). "Releasing TNF-α can at early stages of infection has been reported to have a positive feedback on phagocytosis." (PMID 26828477, 2016). "Membrane expressed TNF allowed cell-cell signalling and control ofacute M. tuberculosis infection although long-term infection control additionallyrequired soluble TNF20." (PMID 26931771, 2016).
infection (continued). "We found a significant increase in levels of IFN-α and IFN-β, interferon-stimulated genes (ISGs) CXCL-10 and ISG15, and the proinflammatory cytokines interleukin-6 (IL-6) and tumor necrosis factor (TNF) at 16 to 24 hpi following infection with N1040A." (PMID 27965448, 2016). "The TNFα gene is also a key molecule of inflammatory process contributing to the activation of leukocytes and their recruitment to the infection site." (PMID 27540375, 2016). "We found higher expression levels of IL1-β and TNFα at different times post-infection in injured larvae compared to injured but uninfected larvae." (PMID 27540375, 2016). "After anti-CD3/CD28 mAb stimulation, TIM3+PD1– T cells produced more IFNγ and TNF than other T cells even late during infection." (PMID 26967901, 2016). "The IL-6 modulates the immune response to the initiation of detrimental infection and damage, and TNF-α, a pro-inflammatory cytokine derived from macrophages and monocytes, performs similar functions." (PMID 27501393, 2016). "The greatest effect of ERK inhibition was observed in spleen samples, where there was a significant decrease in the secreted levels of IFN-γ, MCP-1, IL-6, and TNF-α in mice treated with PD0325901 prior to infection (at day −1) compared to PBS-treated controls." (PMID 27714591, 2016). "Titers of TNF-α, IL-6, IL-12, and IL-4 after infection changed at same level between LI and LM infections." (PMID 27375558, 2016). "Pro-inflammatory cytokines (IFN-γ, IL-18, IL-6, TNF-α) and chemokines (CCL2, CCL5, CCL7, CXCL1, CXCL10) were found to be increased in sera of ZIKV-infected mice, indicating that infection causes systemic inflammation." (PMID 27163257, 2016). "The combination of anti-HMGB-1 and anti-TNF-α was more effective in improving the survival rates when treatment was started between 7 hours and 11 hours after infection, compared to using only anti-TNF-α." (PMID 27556404, 2016). "This acidification likely occurs early in the infection cycle, since fusion of LCVs and lysosomes can be observed within an hour of infection in BMDM pre-treated with TNF." (PMID 27105352, 2016). "At 4 h post-infection, the transcription levels of IL-10, IL-6 and TNFα were reduced in the legS2 infected monolayers as compared to the JR32 infected monolayers." (PMID 26741365, 2016). "The analysis of the TNFα and IκB protein levels revealed that infection with INF B induced TNFα and IκB ratio earlier at 16 hpi, higher than that observed in mock infection in both cell lines." (PMID 27042352, 2016). "For the present purpose, we established a rat inflammation model using ip injection of LPS (4 mg/kg, BW) to mimic an infection and found that LPS significantly increased TNF-α and IL-1β levels in the plasma and brain cortex." (PMID 26968975, 2016). "Unlike H5N1, H1N1 induced significantly lower levels of IL-6, MCP-1 and TNF-α at 24 h post-infection; and MCP-1, TNF-α, IL-10, IFNL1 and IFN-β at 48 h post-infection when compared with H7N9-CK or H7N9-HU." (PMID 26975414, 2016). "CBA/J mice were infected intratracheally with 104C. neoformans and injected with a single dose of isotype or anti-TNF-α neutralizing antibody at the time of infection." (PMID 27406560, 2016). "Ierna and colleagues have shown that soluble TNF-α is required for expulsion of T. spiralis in mice, and IL-1β has been suggested to be an important initiator of the inflammatory response during infection." (PMID 27267469, 2016). "We specifically investigated the role of early plasma TNF-α and IL-10 as predictors of hypersusceptibility to infections after burn." (PMID 27761434, 2016). "We analyzed mRNA levels of TNFα in brains at 3 and 6 days after infection by qRT-PCR together with the viral N protein analyzed above." (PMID 27336830, 2016).
infection (continued). "During infection, MΦs are stimulated concurrently with IFNs and TNFα and amplify inflammation through the production of additional IFNα/β and TNFα." (PMID 27621733, 2016). "The anti-TNF-α Ab suppressed IL-6, MCP-1, and IFN-γ levels, suggesting that the severe response to infection was triggered by TNF-α." (PMID 26844767, 2016). "A literature survey shows that normal TNF-α plasma levels are well below 20 pg/ml and increase to 100–200 pg/ml during infection, only reaching 500–1000 pg/ml at the peak of severe septic shock." (PMID 27603666, 2016). "Expression of the inflammatory cytokines TNF-α and IL-6 is rapidly induced in response to stimulation by antigens, infection, and stress, and are transcriptionally regulated by NF-κB24." (PMID 27625297, 2016). "The results demonstrate that the level of mRNA expression of IL-6, IL-8, IL-10, COX-2, IL-1β, IL-18, and TNF-α were significantly upregulated in peripheral blood monocytes following infection with H. parasuis for 3 or 6 h (p < 0.01)." (PMID 27502767, 2016). "The M1 macrophages, unlike the M2 macrophages, produce NO and other pro-inflammatory cytokines such as the TNF-α, IL-6 and IL-1β to fight infection." (PMID 26934748, 2016). "At 12 h post-infection, the mean level of TNF-α was significantly higher for H7N9-HU (220-fold) than that of H7N9-CK (55-fold) (P = 0.010)." (PMID 26975414, 2016). "TNF-α treatment leads to increased binding of p65 to the HIV-1 R-U5 region after infection by both NL4-3 WT and D116N viruses." (PMID 27167871, 2016). "As a key proinflammatory cytokine, TNF-α plays important roles in resistance to infection and cancer, but exerts pleiotropic and complex functions in the context of TB." (PMID 26881918, 2016). "Critically, on day 4 post-infection, IL-1β, TNFα, IL-6, CCL2 and CCL5 concentrations were significantly reduced in BAL fluid while IL-6 and IL-18 were reduced in the sera." (PMID 27283237, 2016). "In particular, TNF-α production contributes to the initiation of protective immunity during the early post-infection period, whereas the increase in IL-10 production that occurs in response to M. tuberculosis infection suppresses the protective Th1 response." (PMID 27148227, 2016). "As in the in vivo experiments, the expression patterns of NF-κB, TNF-α and MyD88 in lungs were similar to those of gga-miR-19a throughout the test stages after infection." (PMID 27683641, 2016). "Thissuggests a crucial role of innate myeloid cells in terms of both secretion andresponse to TNF in the early steps of infection, while T-cells are less involved inthe TNFR1 mediated response to TNF after M. tuberculosis infection." (PMID 26931771, 2016). "Treatment of host cells with mbcd prior to infection with OMVs from Campylobacter jejuni resulted in reduced production of IL‐8, IL‐6 and TNF‐α." (PMID 27529760, 2016). "Although the production of proinflammatory cytokines (e.g., TNF-α and IL-6) by macrophages/microglia is essential in early host defense against infection, excessive accumulation of these cytokines disrupts systemic or CNS homeostasis." (PMID 27191001, 2016). "They secrete IFN-γ and TNF-α in mice infected with oral pathogen Toxoplasma gondii, recruiting myeloid cells that cease infection." (PMID 27774092, 2016). "Hypoxia, which occurs at sites of infection or inflammation where TNF is expressed, suppressed this IL-10-STAT3 autocrine loop and expression of late phase genes." (PMID 27558590, 2016). "We show that IL-17-mediated inflammation correlated with production of inflammatory cytokines (such as IL-6, IL-1β and TNF-α) that were profoundly increased at the early times upon infection including CLP treatment." (PMID 27389701, 2016).